SIGLEC9 (sialic acid binding Ig like lectin 9)
Diseases named in the same sentence as SIGLEC9 in open-access papers (continued):
Sharing a sentence is not in itself a finding about the gene and the disease.
tumor (continued). "It is worth mentioning that the hypersialylation tumour cells are capable of binding to the Siglec9 on NK cells and modulating immunosurveillance." (PMID 32322597, 2020). "Firstly, Sia, the ligand of Siglec7 and Siglec9 expressed on the surfaces of tumour cells, is correlating with the immune evasion in cancer." (PMID 32322597, 2020). "The fact that tumour cells escape from NK cell attack through the interaction of cell surface sialyl-decoration with Siglec7 and Siglec9 on NK cells makes the two lectins promising target in antitumor drug development." (PMID 32322597, 2020). "Siglec9 promoted tumour cell adhesion process through the recognition of MUC16 glycans which contain α2,3-linked Sia, the ligand of Siglec9." (PMID 32322597, 2020). "Additionally, SIGLEC9+ TAMs high infiltration served as an independent prognostic marker for overall survival, even after adjusting for age, tumor size, FIGO staging, histological type, and lymph node invasion." (PMID 41418390, 2025). "Additionally, SIGLEC9 expression was notably upregulated in tumor stage according to the TCGA database." (PMID 41418390, 2025). "Finally, TPD can also target POI from the tumour microenvironment which play an essential role in tumour growth, such as the glycoimmune checkpoints Siglec‐7 and Siglec‐9." (PMID 40266852, 2025). "SIGLEC9+CD4+T-cells infiltrated around the tumor nests, and MUC1 was expressed in the tumor nests." (PMID 41418390, 2025). "Moreover, recent experiments conducted in a humanized immunocompetent mouse model demonstrated that blocking SIGLEC7 or SIGLEC9 reduces tumor burden in vivo, providing support for the use of anti-SIGLEC antibodies as a means to enhance anti-tumor immunity." (PMID 38311726, 2024). "The enrichment of IL-6/JAK-STAT3 and IL-2/STAT5 signaling pathways in low SIGLEC9 expression suggests that lower SIGLEC9 levels may activate pro-inflammatory pathways that support an anti-tumor immune response by enhancing cytotoxic T cell activity." (PMID 39727942, 2024). "Immunohistochemistry was used to analyze the expression of SIGLEC9 in tumor tissue microarray." (PMID 37207210, 2023). "Ligands on pathogens or tumor cells bind SIGLEC9 on neutrophils and limit neutrophil activation." (PMID 37133224, 2023). "Further verification is needed as to whether Siglec9 is also involved in promoting the tumor progression process of such proteins." (PMID 37106774, 2023). "MUC1-sialylated O-linked glycans on tumour cells binding to Siglec9 did not recruit SHP-1 or SHP-2 but induced calcium flux that lead to the activation of MEK-ERK kinases." (PMID 32322597, 2020). "MUC1 also binds to Siglec‐9 on the surface of bone marrow cells such as tumor‐associated macrophages (TAMs) and DCs, promotes the secretion of factors related to tumor progression, and activates the MEK–ERK signaling axis to regulate the phenotype of TAMs in the TME to promote tumor progression." (PMID 37666495, 2024). "Given the complexity of the TME and the interplay between various immune markers, elucidating the relationship between SIGLEC9 expression and tumor characteristics could significantly enhance our understanding of its prognostic value and potential as a therapeutic target." (PMID 39727942, 2024). "The expression of SIRPA, LILRB1, LILRB2, Siglec1, Siglec7, Siglec9, PDCD1, CD163 and MARCO are preferentially expressed on Mono01, Mono02 and Macro03, suggesting their tumor-promoting roles." (PMID 40755770, 2025). "Lastly, multi-immunofluorescence staining revealed interactions between SIGLEC9+ T-cells and MUC1 in the tumor microenvironment." (PMID 41418390, 2025). "The enrichment of proliferative and metabolic pathways, coupled with the suppression of genes linked to angiogenesis and hypoxia, suggests that SIGLEC9 may support cancer cell adaptation to challenging tumor conditions without engaging processes like angiogenesis." (PMID 39727942, 2024).
tumor (continued). "While comparing between matched and unmatched tumour and normal tissue samples, upregulation of checkpoint receptor genes, notably CD47, CTLA4, HAVCR2, PVRIG, SIGLEC7, and SIGLEC9, were specifically detected in malignant compared to normal tissues." (PMID 39877370, 2024). "For a deeper understanding of the interactions between the expression of SIGLEC9 with the molecular processes that occurred in the TME, we performed GSEA on the CRC tumor data." (PMID 39727942, 2024). "We explored the differential expression of the SIGLEC family in tumor and normal tissue in GEPIA and found that the content of CD22, SIGLEC7, and SIGLEC9 in the tumor was higher than that in normal tissue." (PMID 37207210, 2023). "Similar to MUC1, Siglec9 can interact with MUC16 expressed on epithelial ovarian cancer cells, protecting tumour cells from immune attacking." (PMID 32322597, 2020). "SIGLEC9 belongs to the SIGLEC family of pattern-recognition receptors on immune cells that can bind to a range of sialoglycan ligands, leading to evasion of innate immune responses and tumor progression." (PMID 36688997, 2023). "The expression of SIGLEC9 in tumor tissue without metastasis was higher than that in tumor tissue with metastasis." (PMID 37207210, 2023). "It has been found that tumor cells can express sialylated ligands for SIGLEC receptors on immune cells, depressing immune cell function to escape immune surveillance, such as SIGLEC7 and SIGLEC9 on natural killer cell." (PMID 33240817, 2020). "Since former studies have found SIGLEC1 (CD169), SIGLEC2 (CD22), SIGLEC3 (CD33), SIGLEC7, SIGLEC9, and SIGLEC15 expressed by immune cell populations could be manipulated by tumor cells to escape immune surveillance, we focused on the five SIGLEC family members." (PMID 33240817, 2020). "Moreover, SIGLEC9 expression did not significantly differ depending on the TNM scale parameters, tumor stage, or TILs (p > 0.05)." (PMID 39727942, 2024).
cancer (11 papers, 2020 to 2025). A tumor composed of atypical neoplastic, often pleomorphic cells that invade other tissues. "Siglec7 and Siglec9 are very similar in distribution, gene encoding, protein sequences, ligand affinity, and functions in regulating the immune system against virus and cancers, but differences still exist between them." (PMID 32322597, 2020). "Studies have suggested that high SIGLEC9 expression is associated with reduced survival in cancer patients, and the present findings supported this by showing that patients with high SIGLEC9 expression had a lower survival probability than those with low expression." (PMID 41418390, 2025). "Subsequently, the authors compared the expression levels of SIGLEC9 in normal and cancer tissues through the TNMPlot database." (PMID 41418390, 2025). "The expression of SIGLEC9 has been studied in various cancers, with divergent results regarding its upregulation or downregulation in cancer tissues." (PMID 39727942, 2024). "In various malignancies, SIGLEC9 was expressed differently depending on the clinical stage of a patient or a molecular subtype of the cancer." (PMID 39727942, 2024). "Considering SIGLEC9′s effect on immune responses and its potential role in tumorigenesis, it has recently been proposed as a target in various anti-cancer strategies." (PMID 39727942, 2024). "Cancer cells pretreated with sialidase or PBS were stained with the Siglec9-Fc protein and a fluorescently labeled secondary antibody, which was then analyzed for differences in fluorescence intensity." (PMID 37106774, 2023). "It was found that upon the suppression of LINC01004 or SPI1 and the subsequent SIGLEC9 inhibition, the DNA synthesis ability, and the migration and invasion activities of cancer cells were significantly suppressed, along with increased necrosis rate of cells." (PMID 36688997, 2023). "In macrophages (proliferating) and macrophages subsets, the expression of SIGLEC9 in cancer tissues was higher than that in adjacent tissues." (PMID 35756603, 2022). "Both IHC and Western blotting results indicated high expression of SIGLEC9 in cancer tissues." (PMID 41418390, 2025). "This differential expression of SIGLEC9 in immune subtypes may help elucidate its varied roles in cancer prognosis." (PMID 41418390, 2025). "Emerging evidence suggests that SIGLEC9 could be considered as a new immune checkpoint and target for cancer immunotherapy." (PMID 41418390, 2025). "This means that SIGLEC9 may perform different functions depending on the cancer type, influencing the clinical characteristics and survival of the patients." (PMID 39727942, 2024). "Suppression of genes related to apoptosis and inflammation indicates that SIGLEC9 may support cancer cell survival." (PMID 39727942, 2024). "The signal intensity suggested that Siglec9-Fc ligands were present on all cancer cells." (PMID 37106774, 2023). "Previous studies have explored the correlation between SIGLEC9 and cancers." (PMID 35756603, 2022). "Additionally, SIGLEC9 is involved in the innate immune response to cancer." (PMID 36803349, 2023). "Finally, our Siglec9-Fc product was used to analyze the potential ligands on cancer cell lines." (PMID 37106774, 2023). "Finally, as MUC1-ST-induced macrophages are induced through interaction with Siglec-9 on monocytes, targeting the Siglec9/MUC1-ST interaction could effectively inhibit the production of the pro-cancer MUC1-ST-induced macrophages and impact on survival." (PMID 33149188, 2020). "We therefore, chose three representative cell lines, A549, HeLa, and PANC‐1, for each cancer type and tested the contribution of DSG2 to the trans Siglec‐9 signaling in these cell models." (PMID 39813162, 2025). "Among the Siglecs, SIGLEC9 (CD329) is a promising immune checkpoint target that, when blocked, enhances the body's anti-cancer immune response." (PMID 41418390, 2025). "We measured SIGLEC9 protein concentrations in tissue homogenates of CRC and cancer-free surgical margins." (PMID 39727942, 2024).
cancer (continued). "In our study, we did not observe significant correlations between the expression of the SIGLEC9 protein and the parameters of the TNM scale or the cancer stage." (PMID 39727942, 2024). "MUC1 on cancer cells has been reported to bind to SIGLEC9 on macrophages to re-educate the macrophages and help release factors linking to TME and cancer progression." (PMID 36688997, 2023). "The findings revealed a trend of increased expression of SIGLEC9 in cancer tissues, although this increase was not statistically significant." (PMID 41418390, 2025). "While DGS2 is likely not the only ligand for Siglec‐9 in A375 or other cancer cells we tested, it could be a major functional ligand in A375 cells, because its binding to Siglec‐9 might trigger strong suppressive signals for phagocytosis." (PMID 39813162, 2025). "Importantly, the functional importance of DSG2/Siglec‐9 interaction could be replicated in lung cancer and cervical cancer cell lines with high DSG2 expressions, suggesting DSG2 might be a potential target in cancer immunotherapy." (PMID 39813162, 2025).
infection (5 papers, 2019 to 2022). The state of being infected such as from the introduction of a foreign agent such as serum, vaccine, antigenic substance or organism. "Binding to the inhibitory receptors Siglec‐3, Siglec‐5, Siglec‐9, and Siglec‐11 suppresses the pro‐inflammatory response, which could contribute to decreased clearance of infection and contribute to the relative paucity of symptoms." (PMID 30697344, 2019). "And the expression profile of Siglec9 has not been reported in the infection process in HIV and HCV so far." (PMID 32322597, 2020).
neurodegenerative disease (1 paper, 2023). A disorder of the central nervous system characterized by gradual and progressive loss of neural tissue and neurologic function. "Regarding the MR findings of CD33 (SIGLEC‐3) in AD and SIGLEC‐9 in ALS, we note that several members of the SIGLEC protein family have been implicated for roles in neurodegenerative diseases, especially due to neuroinflammatory properties." (PMID 36504281, 2023).
neurological disease (1 paper, 2025). "Also, 59 unique proteins were associated with AD, and 10 of them (17%) showed an association with AD and an additional neurological disease (CTF1, NSF and PRSS53 with PD; SIGLEC9 with ALS; CR1, CTSH, PARP1 and PVR with MS; LRRC37A2 with both PD and ALS; and IDUA with PD, ALS and MS)." (PMID 40037332, 2025).
SIGLEC9 also shares sentences with these, for which no sentence is quoted: asthma (3 papers); Parkinson disease (3); Alzheimer disease (2); adenoid cystic carcinoma (1); angiosarcoma (1); autoimmune disease (1); cholangiocarcinoma (1); colon cancer (1); COVID-19 (1); Crohn disease (1); esophageal carcinoma (1); Graves disease (1); head–neck squamous cell carcinoma (1); kidney chromophobe (1); kidney tumors (1); low grade glioma (1); meningitis (1); multiple sclerosis (1); ovarian carcinoma (1); pancreatic adenocarcinoma (1); pneumonia (1); psoriasis (1); skin cutaneous melanoma (1); stomach adenocarcinoma (1); tenosynovial giant cell tumor (1); testicular germ cell tumor (1); thyroid carcinoma (1); uterine cancer (1).